APP (amyloid beta precursor protein)
Diseases named in the same sentence as APP in open-access papers (continued):
Sharing a sentence is not in itself a finding about the gene and the disease.
Down syndrome (continued). "Additionally, the etiology of early-onset AD has been attributed to the duplication of the APP locus as well as to trisomy of chromosome 21, which causes Down syndrome." (PMID 37465125, 2023). "Additionally, individuals with Down syndrome are at greater risk for AD because they have three copies of chromosome 21 (the locus of APP gene), which results in a greater production of beta amyloid (Aβ) compared to normal control." (PMID 35369094, 2022). "If a hypothesis based on synaptic plasticity is correct, it follows that the cause of AD in Down’s syndrome is hyperfunction of APP." (PMID 35865745, 2022). "The presence of Aβ peptides in senile plaques of AD patients, as well as the location of the APP gene on chromosome 21, which causes Down’s syndrome, have originally reinforced the amyloid cascade hypothesis." (PMID 34066371, 2021). "The overexpression of APP due to duplication of chromosome 21 in trisomy 21 (Down’s syndrome) has also been reported to cause an early appearance of Aβ1–42 plaques and development of AD at an early age (about 50% of people with Down syndrome who are in their 60s have AD)." (PMID 34199883, 2021). "Additionally, extra copies of the APP gene caused by chromosomal duplication in patients with Down syndrome can promote AD pathogenesis, indicating the pathological involvement of the APP gene dose in AD." (PMID 35822056, 2021). "This matches the fact that in autosomal dominant forms of AD linked to APP or presenilin mutations and in Down syndrome, an overproduction of amyloid peptides is thought to trigger the AD process, along with all its consequences, including tau protein hyper-phosphorylation, in particular." (PMID 33008460, 2020). "Additionally, increased copy number of the APP gene, as it occurs in early onset AD associated with gene duplication and Down’s syndrome, also result in severe Aβ-CAA." (PMID 32414028, 2020). "We reasoned that the increase could affect APP, a key gene in AD pathogenesis that is causal in familial AD and Down syndrome through mutations and, in particular, CNVs: mosaically increased APP CNVs in SAD brains may drive pathology." (PMID 32457796, 2020). "The therapeutic value of inhibiting translation of the amyloid precursor protein (APP) offers the possibility to reduce neurotoxic amyloid formation, particularly in cases of familial Alzheimer’s disease (AD) caused by APP gene duplications (Dup–APP) and in aging Down syndrome individuals." (PMID 30823541, 2019). "Altered metabolism of APP has been shown to associate with mitochondrial dysfunction in primary cortical neurons in AD and in other disease conditions associated with anomalous Aβ processing such as in down’s syndrome." (PMID 30853886, 2019). "In sum, our data suggests that β-amyloid, a pathogenic outcome of increased APP levels, in Down syndrome could contribute to the remodelling of GABA synapses by altering their subunit composition." (PMID 29168008, 2018). "Besides, duplication of the APP locus on chromosome 21 in Down syndrome cause age-related dementia with brain parenchymal Aβ deposits." (PMID 30542277, 2018). "iPSC-derived neurons from fAD cell lines over-expressing APP (cell lines from patients with Down’s syndrome), or with APP mutations, have increased total tau and increased tau phosphorylation at the following key sites; Thr231, Thr181, Thr212, Thr205, Ser202 and Ser396." (PMID 30387070, 2018). "This may happens in a percentage of familial Alzheimer’s disease (AD) cases linked to mutations in genes encoding APP, and presenilin 1 and presenilin 2 which are enzymes involved in the cleavage of APP, or in Down syndrome." (PMID 24634659, 2014). "A similar situation of 50% increased APP gene dosage due to trisomy 21 is associated with >50% increase in APP mRNA expression, and may contribute to early onset AD in Down’s syndrome." (PMID 25031632, 2014).
Down syndrome (continued). "Indeed, patients with Down syndrome have a high risk of developing AD possibly due to trisomy of the APP gene which leads to increased APP expression." (PMID 25126078, 2014). "Although the main cause of AD in Down syndrome individuals is likely to be the additional copy of the APP gene encoded by chromosome 21, mice overexpressing APP (which encodes amyloid beta A4 protein) do not fully recapitulate all the AD-like phenotypes seen in Down syndrome mouse models." (PMID 24396150, 2014). "Additionally, the mutation spectrum extended to APP locus duplications underscoring the importance of APP gene dosage in AD, already observed in the case of Down syndrome." (PMID 24377094, 2013). "It has been suspected that APP contributes to the predisposition to hematologic malignancy in Down syndrome patients and that APP aberration might predispose to cancer." (PMID 23801940, 2013). "Similarly, in the Down syndrome, the presence of a third APP copy gene causes an Aβ overproduction, which explains why the patient with Downs syndrome develops AD pathology in their brains." (PMID 23970926, 2013). "Although disorders of APP cleavage have been implicated in the etiopathogenesis of AD, experience with Down syndrome (DS) raised the possibility that hyper-expression of the APP gene may contribute to Aβ production in some forms of sporadic AD." (PMID 19881909, 2009). "Not only was Aβ peptide identified first from amyloid deposited in vascular walls in AD and Down’s syndrome patients, but the APP mutations were also identified for the first time in a familial form of CAA called hereditary cerebral haemorrhage with amyloidosis – Dutch type (HCHWA-D)." (PMID 19468344, 2009). "As Down syndrome, in which patients demonstrate the same neuropathological changes as AD patients (i.e., senile plaques and neurofibrillary tangles), is caused by a trisomy of chromosome 21, which is where APP is located, the association between the APP gene and AD has attracted much attention." (PMID 35799899, 2022). "We crossed Down syndrome mouse models with partial trisomies, to an APP transgenic model and found that extra copies of subgroups of chromosome 21 gene(s) modulate amyloid-β aggregation and APP transgene-associated mortality, independently of changing amyloid precursor protein abundance." (PMID 33707583, 2021). "Collectively, these data reveal an important role for APP in the amyloidogenic aspects of AD but challenge the idea that increased APP levels are solely responsible for increasing specific phosphorylated forms of tau or enhanced neuronal cell death in Down syndrome-associated AD pathogenesis." (PMID 29861166, 2018). "Moreover, elevation of APP was associated with a decreased BACE1-mediated processing of CHL1 not only in 12 months old 5XFAD mice but also in human brains from subjects affected by Down syndrome, most likely due to substrate competition." (PMID 29391027, 2018). "Furthermore, our findings suggest that BACE1 inhibition could exacerbate mechanism-based side effects in conditions associated with APP elevation (e.g. Down syndrome) owing to impairment of BACE1-mediated processing of CHL1." (PMID 29391027, 2018). "In Down syndrome, the presence of three copies of chromosome 21 leads to overexpression of key genes, including APP and DYRK1A." (PMID 41465426, 2025). "AD in Down syndrome is often attributed to elevation of APP because the APP gene is on human chromosome 21 which is triplicated in Down syndrome." (PMID 40599392, 2025). "For example, in Down syndrome, trisomy of chromosome 21 and elevated APP levels are used as genetic and molecular biomarkers." (PMID 41465426, 2025). "Such APP‐positive dystrophies are a long‐standing finding in Down syndrome and early onset AD and also serve as a marker of axonal injury in non‐AD pathology, and it has been previously noted that they are relatively uncommon in late onset AD." (PMID 39084860, 2025).
Down syndrome (continued). "In this respect, it has been noted in mouse models of trisomy 21 as well as in iPSC‐derived Down syndrome neurons, that chromosome 21 genes other than APP exacerbate AD pathogenesis." (PMID 39084860, 2025). "Overexpression of the APP gene, located on chromosome 21, has been observed in the brains of individuals with Down syndrome, and Down syndrome progresses in a manner similar to that of Alzheimer’s disease." (PMID 41153388, 2025). "Its triplication in Down Syndrome patients leads to APP overexpression and an increased production of Aβ peptides." (PMID 40725224, 2025). "Conversely, accumulating the APP gene as observed in Down syndrome (Trisomy 21) leads to pathological brain states with increased risks for the development of AD." (PMID 40739894, 2025). "ADAD includes patients with duplications or mutations in PSEN1, PSEN2 and APP genes, and individuals with Down Syndrome (DS) that have an additional APP gene due to the presence of this gene on their extra chromosome 21." (PMID 40634156, 2025). "Posiphen lowered APP translation in cell and animal models and showed beneficial effects on cognition in APP and Down syndrome transgenic mice." (PMID 38970127, 2024). "Genetic factors play a significant role, with overexpression of the amyloid precursor protein (APP) gene linked to the disease, notably seen in trisomy 21 (Down syndrome) patients." (PMID 39201317, 2024). "Individuals with Down syndrome (trisomy of chromosome 21) harbour three copies of the APP gene and invariably develop progressive AD with highly characteristic neuropathological features." (PMID 38527856, 2024). "Here, lysosomal dysfunction was shown to occur when APP is overexpressed in Down syndrome (triple APP) and in Alzheimer mouse models so as to proportionately also increase APP CTF (see citations." (PMID 38927051, 2024). "However, BACE-1 inhibition might lead to APP (substrates of BACE-1) elevation and impair BACE1-mediated processing of endogenous CHL1 (cell adhesion molecule L1-like protein), exacerbating mechanism-based side effects in, e.g., Down syndrome associated with APP elevation." (PMID 38212785, 2024). "Overproduction of APP in Down Syndrome (trisomy 21) results in AD pathology developing inevitably with age." (PMID 38970127, 2024). "Patients with Down syndrome exhibit either complete or partial trisomy of chromosome 21 (which carries APP and some other AD-related genes)." (PMID 39120323, 2024). "Persons with Down syndrome contain an additional APP copy and experience accelerated plaque accumulation." (PMID 39441557, 2024). "Additional support for the importance of vascular contributions to AD pathogenesis comes from studies of individuals with trisomy 21 (Down syndrome) who have an additional copy of the APP gene." (PMID 37238700, 2023). "As the APP gene exists on Chromosome 21, excess Aβ peptides occur in Trisomy 21-T21 (Down’s Syndrome)." (PMID 37808474, 2023). "We found that dye 60 was particularly useful for discriminating conformational strains of Aβ plaques across four neurodegenerative diseases—sAD, fAD PSEN1, fAD APP, and Down syndrome (DS)." (PMID 36927157, 2023). "Their original theory primarily focused on the frequent occurrence of AD in Down’s syndrome patients due to the generation of significant amounts of Aβ-peptides since the amyloid precursor protein (APP) gene is positioned on the three 21 chromosomes." (PMID 37239068, 2023). "For example, studies have suggested that in rare cases of duplication of the APP locus or in cases of trisomy 21 (Down syndrome) individuals go on to develop early-onset AD and show increased Aβ production in the brain." (PMID 37465125, 2023). "For example, individuals with Down syndrome (DS) are likely to produce excess APP because Down syndrome is genetically characterized by an extra copy of chromosome 21 where APP is located." (PMID 37117484, 2023).
Down syndrome (continued). "Stimulation of mTOR signalling has been observed in response to accumulation of Aβ, and hyperactivation of mTOR is observed in Down's syndrome (in which the dosage of the APP gene is increased because it resides on chromosome 21 and early-onset AD is common)." (PMID 34842276, 2022). "Here, we determine if primary mouse embryonic fibroblasts isolated from a mouse model of Down syndrome can be used to study endosome and APP cell biology." (PMID 35544526, 2022). "In case of Down’s Syndrome, where three copies of the APP gene exist due to trisomy, epilepsy is observed in 84% of cases." (PMID 34121170, 2021). "Those with Down’s Syndrome, who express ≈ 50% more APP than normal individuals, will have an AD prevalence that is much more than 50% higher." (PMID 34280181, 2021). "Overexpression of the APP gene significantly increases both AD severity and progression rate, particularly observed in individuals with Down Syndrome (Trisomy 21), who have three copies of this gene and demonstrate AD symptoms as early as 40 years of age." (PMID 34209883, 2021). "Previous studies have shown that ADAMTS1, within 665 kb of APP on chromosome 21, has elevated expression in Down’s syndrome and LOAD brain and is a potential neuroprotective gene or neuroinflammatory gene important to microglial response." (PMID 33419465, 2021). "For individuals with Down’s Syndrome, the trisomy of chromosome 21 results in life-long levels of APP that are ≈ 1.5 times that of normal individuals and an AD incidence at least 3 times higher." (PMID 34280181, 2021). "When analysing Aβ isoforms generated by cerebral organoids, there was an increase in Aβ1‐19 and Aβ1‐34 relative to amyloidogenic species (Aβ1‐40 and Aβ1‐42) in Down's syndrome organoids when compared to isogenic diploid cells and APP duplication organoids." (PMID 33539581, 2021). "For example, Down’s syndrome patients with chromosome 21 trisomy where APP is located can have Alzheimer-like pathology." (PMID 34276768, 2021). "Almost all adults with Down syndrome (DS) display neuropathological changes of AD over 40 years of age due to extra copies of APP attributed to the trisomy of chromosome 21." (PMID 35822056, 2021). "Second, overexpression of APP impairs primary cilia both in a mouse AD model and in individuals with Down syndrome, harboring three copies of APP39,40." (PMID 34580355, 2021). "An APP gene dose effect triggering AD development, as occurs in Down syndrome and in gene duplication processes, is a further/an additional potential factor contributing to amyloid pathogenesis." (PMID 33008460, 2020). "In Down syndrome increased production of APP-βCTF has been shown to impair lysosomal acidification and function." (PMID 32218723, 2020). "Many Down syndrome patients develop AD resulting from an extra copy of the APP gene due to trisomy on chromosome 21." (PMID 33069246, 2020). "APP shows a clear gene dosage effect, where three copies of APP in Down syndrome or rare familial AD cases are sufficient to produce AD neuropathology and/or symptomology." (PMID 32457796, 2020). "In patients with Down syndrome who carry an extra copy of APP, APOE4 appears to hasten the onset of AD and accelerate the progression of neurodegeneration." (PMID 32580938, 2020). "The strongest evidence for the involvement of APP and its cleavage product Aβ in AD comes from familial AD and Down syndrome studies." (PMID 32457796, 2020). "APOE*ε2 also protects against AD in Down’s syndrome (DS) patients whose amyloid-beta precursor protein (APP) gene is triplicated." (PMID 33148290, 2020). "Studies have additionally shown widespread α-syn accumulation in the neocortex and limbic systems of patients with Down syndrome, sporadic Alzheimer’s disease (AD), and familial AD from presenilin 1 (PS1) and amyloid precursor protein (APP) mutations." (PMID 32680537, 2020).
Down syndrome (continued). "Aggregate containing the carboxy terminal fragment of APP (APP-βCTF) have been found in Down Syndrome, a neurodevelopmental disorder with pathological features common to the early onset forms of AD." (PMID 32218723, 2020). "In Down syndrome the extra gene copy of APP gene (on chromosome 21) leads to increased production of APP-βCTF." (PMID 32218723, 2020). "Studies on Down syndrome (Trisomy 21), representing cases of elevated expression of APP, AD patient fibroblasts, AD mouse models, and recent studies using patients iPSCs have all shown evidence of a defective endolysosomal network." (PMID 33290404, 2020). "In Down syndrome (Trisomi-21) there is increased expression of APP due to an extra copy of the APP gene." (PMID 32039447, 2020). "It is noteworthy, that changes in the APP and tau processing have also been described in Down’s syndrome, while tau alterations have been detected in a wide range of neurodegenerative disorders collectively called tauopathies, as well as in aging." (PMID 30971876, 2019). "The APP gene is located on chromosome 21, which explains the higher incidence of early-onset AD in individuals with 21 trisomy (Down Syndrome) and in individuals with APP gene locus duplication [a rare form of early onset of familial origin]." (PMID 31072403, 2019). "The Aβ peptide precursor protein (APP) gene is located on chromosome 21, and trisomy of this chromosome in Down syndrome is the reason that AD is often observed in patients with Down syndrome, which in this case indicates the genetic basis of AD disease." (PMID 32076398, 2019). "DNA methylation dysregulation has also previously been observed in this region in Down syndrome individuals, which is of interest as many Down syndrome patients develop AD due to a duplicate of APP in the trisomy on chromosome 21." (PMID 31133796, 2019). "People living with Down Syndrome (DS) have higher prevalence to develop AD pathology primarily due to overexpression of the APP gene on chromosome 21." (PMID 30885273, 2019). "Wolvetang and colleagues used CRISPR/Cas9 technologies to manipulate the copy number and expression of the amyloid precursor protein (APP) gene in Down syndrome and corresponding euploid pluripotent stem cells." (PMID 29861166, 2018). "Increased dosage of this gene results in an elevated expression of APP in Down syndrome (DS; trisomy 21) tissues." (PMID 29861166, 2018). "In order to further support our finding that increased levels of APP are associated with decreased BACE1-mediated processing of CHL1, we analyzed hippocampal tissue from subjects affected by Down Syndrome (DS) carrying an extra copy of chromosome 21." (PMID 29391027, 2018). "Aβ production can also increase as a result of increased APP expression, such as is seen with APP duplication in Downs’ syndrome." (PMID 30387070, 2018). "To test this in an isogenic human model, we deleted the supernumerary copy of the APP gene in trisomic Down syndrome induced pluripotent stem cells or upregulated APP expression in euploid human pluripotent stem cells using CRISPRa." (PMID 29861166, 2018). "Down syndrome (DS) is primarily due to trisomy of chromosome 21, which includes the amyloid precursor protein (APP) gene." (PMID 29226868, 2018). "Genetic familial effects beyond those associated with the E4 allele have been reported with APP gene dose (trisomy 21/Down syndrome; APP duplication) as well as mutations in PSEN1, PSEN2, and APP." (PMID 29497704, 2018). "We designed a phenotypic small-molecule screen to identify modulators of APP processing in trisomy 21/Down syndrome neurons, a complex genetic model of AD." (PMID 28285880, 2017). "The overexpression of genes on chromosome 21 other than APP is thought to contribute to the AD-like pathology observed in Down syndrome." (PMID 28285880, 2017).